ENSG00000212302
Synonyms: LOC124900351
Gene: Small nucleolar RNA gene on chromosome 14 (22,756,761 to 22,756,829, reverse strand). Ensembl gene ENSG00000212302.
Gene Ontology:
Biological process: RNA processing
Cellular component: nucleolus
Homologues: Orthologues: mouse Gm25506 (78% identical), rat Snord41 (77% identical). Paralogues in human: SNORD41 (88% identical).